RALGAPA2 (Ral GTPase activating protein catalytic subunit alpha 2)
Description:
Catalytic subunit of the heterodimeric RalGAP2 complex which acts as a GTPase activator for the Ras-like small GTPases RALA and RALB.
Synonyms: AS250; C20orf74; KIAA1272; dJ1049G11.4; RapGAPalpha2; bA287B20.1; dJ1049G11; p220
Tractability: Antibody: its Gene Ontology location is reachable by antibodies, with high confidence. PROTAC: ubiquitination databases record sites on it; its protein half-life has been measured.
Gene: Protein-coding gene on chromosome 20 (20,389,530 to 20,712,644, reverse strand). Ensembl gene ENSG00000188559.
Subcellular location: Cytoplasm
Subcellular location (Human Protein Atlas): Cytosol; Plasma membrane
Pathways (Reactome):
Vesicle-mediated transport: Translocation of SLC2A4 (GLUT4) to the plasma membrane
Gene Ontology:
Molecular function: protein binding; GTPase activator activity; protein heterodimerization activity
Biological process: activation of GTPase activity; Ral protein signal transduction; regulation of small GTPase mediated signal transduction
Cellular component: cytoplasm; cytosol; extracellular region; nucleus
Genetic constraint (gnomAD): Loss-of-function variants: 114 observed, 180.7 expected, observed/expected ratio (o/e) 0.63, 90% interval 0.54 to 0.74. The upper end of that interval is the gene's LOEUF score, 0.74, which puts it in group 3 of 6, group 1 being the genes least tolerant of losing a copy. Missense variants: 1,961 observed, 2,055.9 expected, observed/expected ratio (o/e) 0.95, 90% interval 0.92 to 0.99. Synonymous variants: 785 observed, 772.74 expected, observed/expected ratio (o/e) 1.02, 90% interval 0.96 to 1.08.
Homologues: Orthologues: chimpanzee RALGAPA2 (99% identical), macaque RALGAPA2 (99% identical), dog RALGAPA2 (92% identical), mouse Ralgapa2 (91% identical), rat Ralgapa2 (91% identical), rabbit RALGAPA2 (91% identical), pig RALGAPA2 (89% identical), guinea pig RALGAPA2 (85% identical), tropical clawed frog ralgapa2 (74% identical), zebrafish ralgapa2 (66% identical), Drosophila melanogaster CG5521 (34% identical), Caenorhabditis elegans hgap-1 (19% identical). Paralogues in human: RALGAPA1 (55% identical), TSC2 (16% identical).
Diseases named in the same sentence as RALGAPA2 in open-access papers:
RALGAPA2 is named in the same sentence as 7 diseases in open-access papers, as found by Europe PMC text mining. Sharing a sentence is not in itself a finding about the gene and the disease. The quoted sentences say what the papers report.
breast carcinoma (5 papers, 2012 to 2025). "For example, the interaction between MALAT1 target, miR-143-3p, and RALGAPA2 is affected by a functional SNP rs3827693 in breast cancer." (PMID 34746128, 2021).
prostatic intraepithelial neoplasia (1 paper, 2022). "In addition, down-regulation of RALGAPA2, a component of the ‘G-protein alpha-subunit binding’ network, enhances migration and invasion of PC cells and is associated with progression of prostatic intraepithelial neoplasia to PC." (PMID 36169805, 2022).
tumor (5 papers, 2018 to 2025). "All but one of these genes was also identified in selection scans, and two of them were identified in all three transects: Snx25, which is linked to activity, cardiac function, and more recently, circadian pace-making and Ralgapa2, which is linked to neoplasm and glucose homeostasis." (PMID 38968323, 2024). "To provide structural insights into the role of RalGAP complexes as tumor suppressors, we searched for missense mutations in the RALGAPA1, RALGAPA2, and RALGAPB genes in cancer patients." (PMID 40738882, 2025). "RALGAPA2 is located upstream of the tumor regulatory pathway and playing a key role, although it has not been reported in LUSC, and further research is required to determine its importance in this cancer." (PMID 32340320, 2020). "A few differentially expressed genes between the PitNET subtypes also correlate with tumor size (CACNA2D2, CGA, KRT8, RALGAPA2) suggesting a potential role in tumor growth." (PMID 34758873, 2021).
RALGAPA2 also shares sentences with these, for which no sentence is quoted: cancer (2 papers); lung carcinoma (1); Obesity (1); thyroid cancer (1).